NQO1 (NAD(P)H quinone dehydrogenase 1)
Diseases named in the same sentence as NQO1 in open-access papers (continued):
Sharing a sentence is not in itself a finding about the gene and the disease.
cancer (continued). "Finally, 156 case-control studies related to NQO1 rs1800566 polymorphism and cancer risk were obtained." (PMID 36338728, 2022). "Additionally, NQO1 is associated, due to polymorphisms, mutations and altered expression levels, with several diseases such as cancer, Alzheimer’s disease and Parkinson’s disease." (PMID 35740007, 2022). "Stratified analysis of NQO1 rs1800566 C/T variation on cancer susceptibility." (PMID 36338728, 2022). "Since the product of NQO1 gene expression is believed to exert universal antioxidant and cellular protective effects in tissues, our study will help to elucidate the effect and biological significance of this gene polymorphism on overall cancer risk." (PMID 36338728, 2022). "NQO1 is associated with several diseases including cancer, Alzheimer ́s and Parkinson’s disease." (PMID 36504709, 2022). "However, the impact of these mutations on NQO1 multifunctionality and their potential role in cancer development are largely unexplored." (PMID 36504709, 2022). "In this work, we have investigated allosteric communication in the multifunctional, cancer-related and antioxidant protein NQO1 by mutating several fully buried leucine residues (L7, L10 and L30) to smaller residues (V, A and G) at sites in the N-terminal domain." (PMID 35740007, 2022). "Many studies have been believed that environmental factors lead to the change of alleles, which may be explained the inactivation of the NQO1 enzyme may change the susceptibility to some types of cancer." (PMID 36338728, 2022). "Current study shows that rs1800566 polymorphism of NQO1 was linked to cancer susceptibility and maybe as a tumor marker in their development." (PMID 36338728, 2022). "Through this, it was confirmed that the function of NQO1 is not limited to detoxification, but has a two-sided nature that causes detoxification or toxicity for each different substrate, which was presented as a target for cancer treatment." (PMID 34947831, 2021). "In addition, the high expression of NQO1 is associated with a shorter survival time of cancer patients." (PMID 34833955, 2021). "Moreover, single-nucleotide polymorphisms (SNPs) in the NQO1 gene, including the C609T mutation, result in decreased enzymatic activity and have been associated with increased cancer susceptibility." (PMID 34083537, 2021). "Treatment of cancers with β-lapachone causes NAD(P)H: quinone oxidoreductase 1 (NQO1) to generate an unstable hydroquinone that regenerates itself in a futile cycle while producing reactive oxygen species (ROS) in the form of superoxide and subsequently hydrogen peroxide." (PMID 34439319, 2021). "Furthermore, serine substitution of the proline-187 residue, a common cancer-associated polymorphism, in the C-terminal region of NQO1 resulted in NQO1 dimer destabilization and loss of catalytic activity." (PMID 33630938, 2021). "Therefore, upregulation of NQO1 can be combined with new NQO1-activated antitumor agents and cause preferential damage to cancer cells with high NQO1 activity." (PMID 32645959, 2020). "The increased NQO1 expression in cancer is linked to an increased Nrf2 expression." (PMID 32922184, 2020). "Based on loss-of-function disease mechanisms, intact NQO1 might be required for normal cells to survive under stressful conditions because polymorphic forms of NQO1 are associated with an increased risk of cancer and neurodegenerative diseases (such as AD)." (PMID 32645959, 2020). "This compound destabilised wild-type NQO1 and both cancer-associated variants." (PMID 31431515, 2019). "Reduced NQO1 activity is associated with a predisposition to cancer." (PMID 30518535, 2019).
cancer (continued). "Interestingly, a common polymorphic form of human NQO1, p.P187S, is associated with an increased risk of several forms of cancer." (PMID 30518535, 2019). "Interestingly, two polymorphic forms of NQO1 that reduce cellular NQO1 activity are associated with increased risk of cancers." (PMID 30595797, 2018). "Addition of FK866+β-lap to NQO1-overexpressing cancer cells caused a burst of ROS-induced DNA damage and NAD+/ATP depletion in a near-identical manner to the caspase-independent, μ-calpain-mediated cell death pathway induced by lethal doses of β-lap alone, despite the additional energy depletion." (PMID 25590809, 2015). "Also, the disruption of the NQO1 gene or genetic polymorphism increased the risk of chemical-induced toxicity and cancers." (PMID 28983331, 2015). "Genetic variations in NQO1 gene that impede its enzyme function may be considered as putative risk factor for cancer." (PMID 25602258, 2015). "To increase the specificity and efficacy of GLS1 inhibition in PDA, we combined BPTES or CB-839 with ß-lapachone (ß-lap), a targeted cancer therapeutic that causes tumor-selective reactive oxygen species (ROS) formation in an NADPH:quinone oxidoreductase 1 (NQO1)-specific manner." (PMID 26462257, 2015). "Polymorphisms that lead to aberrant alteration of NQO1 activity may have profound impacts on cancer disposition." (PMID 25602258, 2015). "The NQO1 C609T polymorphism has been associated with an increased risk of various malignancies, including lung, esophageal, gastric and uterine cervix cancers." (PMID 25885439, 2015). "Given that the previous studies have consistently shown that the variant T allele resulted in reduced enzymatic activity, it was biologically reasonable to hypothesize a potential relationship between the NQO1 Pro187Ser polymorphism and cancer susceptibility." (PMID 24884893, 2014). "The NQO1 Pro187Ser polymorphism has been found correlated with decreased enzymatic activity of NQO1 and may affect host’s susceptibility to cancer by changing the enzymatic activity of NQO1." (PMID 24884893, 2014). "Despite its importance for cancer prediction and therapy, the exact molecular basis for the loss of function in NQO1 P187S is currently unknown." (PMID 25143260, 2014). "Despite its importance for cancer prediction and therapy, the exact structural and molecular basis for the loss of function in NQO1 P187S is currently unknown." (PMID 25143260, 2014). "NQO1 gene mutations are linked to tardive dyskinesia, which increases the risk of hematotoxicity after exposure to benzene, and susceptibility to various forms of cancer." (PMID 23497461, 2013). "Meta-analysis for the association between the NQO1 609C>T polymorphism and cancer risk." (PMID 22272361, 2012). "β-lap causes NQO1-dependent radiosensitization of cancer cells." (PMID 21998736, 2011). "Our observation of increased prevalence of IM in carriers of the NQO1 609 T allele concurs with earlier reports on its association with various cancers and can be explained by a decreased activity for the detoxification of environmental and dietary carcinogens." (PMID 19822020, 2009). "Therefore, the targets of our future work are the confirmation of this finding (predisposition of patients to the development of cancer by NQO1-polymorphism), and the confirmation of the major role NQO1 in AAI activation." (PMID 21218097, 2008).
cancer (continued). "Many enzymes have been implicated in the catalysis of MMC including NQO1 and interest in NQO1-directed cancer chemotherapy arose following the observation that NQO1 is more highly expressed in tumour tissue when compared with matched healthy tissue, for example lung." (PMID 17031400, 2006). "To establish whether NQO1-induced CKS1 regulates cancer cell cycle progression at G2/M phase, we transfected NQO1-overexpressing cancer cells with siCont and pCont or siCKS1B and pCont, and NQO1-deficient cancer cells with pCont and siCont or pCKS1B and siCont." (PMID 36793872, 2023). "Thus, the presence of LoF variants in NQO1 and increased cancer risk may resemble a recessive inheritance." (PMID 36504709, 2022). "Herein, we characterized the structural and functional consequences of two mutations (the cancer-associated P187S and the phosphomimetic S82D) on different ligation states which are relevant to flavin binding, intracellular stability and catalysis of the disease-associated NQO1 flavoprotein." (PMID 34537677, 2021). "Furthermore, NQO1 polymorphism is associated with the development of certain cancer types." (PMID 32605023, 2020). "Thus, some believe that fully active NQO1 can increase the risk of cancer." (PMID 33313330, 2020). "As the physiological function of NQO1 is to detoxify the potential mutagenic compounds, it can be speculated that the decrease of NQO1 may predispose the cells to more susceptible condition to cancer development." (PMID 31886179, 2019). "For example, the illustration pathway is a simplified version of a cancer-related redox circuit involving the enzyme NQO1 (NAD(P)H:quinone oxidoreductase 1), which is protective against oxidative stress." (PMID 41971098, 2026). "A study conducted on human cancers overexpressing NAD(P)H:quinone oxidoreductase 1 (NQO1) revealed that NQO1 binds directly to the HIF‐1 protein, inhibiting PDH‐mediated proteasomal degradation and stabilising HIF‐1." (PMID 40954549, 2025). "The differential response of sample 1081 to these inhibitors underscores the complexity of targeting NQO1 in cancer treatment, particularly considering the specificity and mechanism of action of the drugs." (PMID 39707614, 2025). "The elevated NQO1 expression in various cancers correlates with tumor progression and chemotherapeutic resistance, which has been exploited for developing tumor-selective prodrugs and molecular imaging agents." (PMID 40630553, 2025). "For instance, TXNRD1 and NQO1, as redox stress-related enzymes, have been reported to be upregulated in various cancers and promote malignant progression." (PMID 41035672, 2025). "NU7026 enhances irradiation and etoposide-produce DNA destruction, causing G2/M arrest and cell death, and synergizes with ß-lapachone to selectively target NQO1-positive cancer cells." (PMID 40256842, 2025). "Cancer cells are characterized by high expression levels for NAD(P)H quinone dehydrogenase 1 (NQO1), a flavoenzyme responsible for two-electron reduction of quinones to hydroquinones." (PMID 41012497, 2025). "NQO1 is a two-electron reductase responsible for quinone detoxification and activation, currently recognized as a therapeutic target for cancer." (PMID 40427075, 2025). "Although, the level of NQO1 in cancer cells is heterogeneous, it can be significantly upregulated in cancer cells upon X-ray irradiation 38-39." (PMID 40585976, 2025). "Background and Objectives: Many studies have demonstrated a relationship between cancer and the NAD(P)H quinone oxidoreductase 1 (NQO1) polymorphism." (PMID 41010895, 2025). "For example, decreased expression of manganese SOD (MnSOD), metallothionein, and NAD(P)H: quinone oxidoreductase 1 (NQO1) is closely linked to the incidence and progression of various cancers." (PMID 40599237, 2025). "The chemotheraputic agent cisplatin is commonly used to treat OSA in both species and significantly upregulates NQO1 in cancer cells, increasing their sensitivity to β-lapachone in vitro and in vivo." (PMID 40566602, 2025).
cancer (continued). "Previous immunohistochemistry study has revealed that NQO1 plays a crucial role in the progression of gastric cancer, distinguishing it from non-cancer patients and healthy controls." (PMID 41333220, 2025). "Recent studies have highlighted the distinct cytotoxic effects of MDM2 and NQO1 inhibitors in various cancer models." (PMID 39707614, 2025). "The use of NQO1 inducers in combination with β-lapachone has demonstrated the importance of combination therapeutic strategies, highlighting their potential in cancer therapy." (PMID 40509203, 2025). "β‐Lap, a natural compound originated from the lapacho tree (Tabebuia avellanedae), is commonly employed in the treatment of various types of cancers that overexpress NQO1." (PMID 40014262, 2025). "Recent studies continue to explore the complex role of NQO1 in cancer pathogenesis and its clinical implications." (PMID 41010895, 2025). "In this study, we showed that β‐Lap induces apoptotic cell death through PKA activation in human cancer cells, and this effect is dependent on the presence of NQO1." (PMID 40014262, 2025). "The overexpression of NQO1 in these tumors supports cancer cell survival by reducing oxidative stress, enabling drug resistance, and facilitating tumor progression." (PMID 40002465, 2025). "The interplay between NQO1 inhibitors and chemotherapeutic-drug-resistant cancers has been revealed as well." (PMID 40002465, 2025). "Despite ongoing debates about the role of NQO1 in cancer, it has been found to be highly expressed in various cancers, including breast cancer, melanoma, lung cancer, cholangiocarcinoma, and pancreatic cancer." (PMID 41333220, 2025). "This reduction in Nrf2 activity was linked to decreased levels of certain proteins that help cancer cells thrive, such as hemeoxygenase-1 (HO-1) and NAD(P)H quinone oxidoreductase-1 (NQO-1)." (PMID 41009025, 2025). "Quinone oxidoreductase (NQO1), a cytosolic flavoprotein, is important for reprogramming cancer cell metabolism." (PMID 39939940, 2025). "This point of view is applied in the design of many drugs that are able to induce NQO1 and thus decrease ROS and prevent carcinogenesis and aid the organism fight against cancer." (PMID 40002465, 2025). "Levels of apoptosis‐related proteins were significantly decreased upon activation of autophagy with rapamycin in NQO1‐expressing cancer cells co‐treated with β‐Lap and CGA." (PMID 40014262, 2025). "The expression of NQO1 in tumors is significantly higher compared to other tissues, establishing NQO1 as a selective biomarker for cancer." (PMID 40710294, 2025). "Clinically, NQO1 is highly overexpressed in many human cancers, including breast, liver, ovarian, and pancreatic cancers, compared with normal tissues." (PMID 39939940, 2025). "The specific results of the inhibition of NQO1 in cancer cells has been shown in the case of berberine, where this compound promoted immunogenic cell death after causing the increased production of ROS and cell oxidative damage." (PMID 40002465, 2025). "The activation of the phosphoinositide 3-kinase (PI3K)/Akt signaling has been shown to increase the expression of NQO1 in several cell types, including pheochromocytoma cells and cancer cells." (PMID 38167027, 2024). "On the cancer front, a dual inhibitor of NQO1 and glutathione transferases, called MNPC (5-methyl-N-(5-nitro-thiazol-2-yl)-3-phenylisoxazole-4-carboxamide), has been synthesized and characterized." (PMID 39120303, 2024). "Previous studies have shown that up-regulation of NQO1 can increase chemoresistance in cancer cells." (PMID 39094401, 2024). "SYZ-30 quickly responded to detect NQO1 activity in tumor cells within 5 min and was suitable for imaging NQO1-positive cancer cells." (PMID 39120303, 2024).
cancer (continued). "The presence of NQO1 in cancer cells triggered the removal of the trimethyl-locked quinone group from NGP-26, thereby restoring its ability to degrade targeted proteins through interaction with E3 ligase VHL." (PMID 38773495, 2024). "Recent meta-analysis studies have demonstrated that the replacement of cytosine with thymidine (609C > T) expresses the substitution of serine for proline, reducing the NQO1 enzyme activity, and resulting in the development of several types of human cancers." (PMID 38922530, 2024). "Our results demonstrated a significant increase in the antioxidant-related genes Nqo1 and Ho-1 in MitoQ-treated cancer cells, indicating that MitoQ induces cancer cell death by reducing ROS levels within cancer cells." (PMID 38732133, 2024). "It had an emission maximum of 695 nm and was able to detect tiny amounts of NQO1 (as low as 4.9 ng/mL or 0.49 mU/mL) in cancer cells." (PMID 39120303, 2024). "For example, NQO1, an enzyme overexpressed in certain cancers, can activate NQO1-PROTACs by cleaving their caging groups." (PMID 39649701, 2024). "In 2016, Kim’s group designed reagent 13 by combining the topoisomerase I drug 7-ethyl-10-hydroxycamptothecin (SN-38) with hydroquinone (activated by NQO1) and biotin for targeting cancer cells." (PMID 39120303, 2024). "GNQ-9 was shown to be an excellent futile substrate for NQO1, with antiproliferative activity against a variety of cancer cell lines, particularly NQO1-overexpressing tumor cells, and minimal cytotoxicity towards a panel of normal cell counterparts." (PMID 39120303, 2024). "Inhibitors targeting NQO1 are being explored as potential therapeutic strategies to counteract its protective effects in cancer cells, thereby increasing their vulnerability to ferroptosis inducers." (PMID 39534872, 2024). "In this potential clinical application, one can envisage a cancer patient obtaining an intravenous injection of the NQO1-targeted fluorescence agent just before surgery." (PMID 39120303, 2024). "This sensitive visualization/quantitation and powerful imaging technology based on NQO1 expression offers promise for guided cancer surgery, and the reagents suggest a theranostic potential for NQO1-targeted chemotherapy." (PMID 39120303, 2024). "Theranostic prodrugs based on NQO1 allow for the monitoring of quinone moiety reduction and release of the parent drug, while also showing selective cytotoxicity against cancer cells." (PMID 38167027, 2024). "This innovative approach leverages the specific overexpression of NQO1 in cancer cells to achieve targeted activation of PDT, minimizing damage to surrounding healthy tissues and enhancing the therapeutic efficacy of the treatment." (PMID 38675124, 2024). "While not the primary focus of this study, it is worth noting that specific SNPs, such as NQO1 rs1800566, exhibit correlations with cancer incidence, highlighting the broader impact of pharmacogenetic variants." (PMID 38675222, 2024). "Starting in 2003, tumor regression in several xenograft studies prompted the possibility of the clinical use of β-lapachone, particularly for NQO1-positive cancers." (PMID 39120303, 2024). "β-Lapachone-induced NQO1-dependent cell death has been reported in several cancers, including lung, breast, and liver cancers." (PMID 39164783, 2024). "Further, the cancer-selective expression of NQO1 has opened excellent opportunities for distinguishing cancer cells/tissues from their normal counterparts." (PMID 39120303, 2024). "We reviewed expression patterns, bioreductive futile substrates, and various fluorescent probes to image and quantify NQO1 activity in human cancers." (PMID 39120303, 2024). "In preclinical models, β-lap-induced cancer cell death occurred across tumors in proportion to tumor NQO1 levels." (PMID 39120303, 2024). "It was effective in monitoring NQO1 in cancer cells using two-photon excitation and demonstrated high photo stability." (PMID 39120303, 2024).